ALB (albumin)
Diseases named in the same sentence as ALB in open-access papers (continued):
Sharing a sentence is not in itself a finding about the gene and the disease.
ovarian carcinoma (104 papers, 2004 to 2026). A malignant neoplasm originating from the surface ovarian epithelium. "Corresponding with the previous studies which identified relevant risk factors of AL in ovarian cancer, low preoperative albumin level and low anastomotic level from the anal verge were resulted in the significant risk factors." (PMID 37120533, 2023). "In previous studies, predisposing factors of anastomotic leak in ovarian cancer were identified including low albumin level (< 3.0 mg/dl), old age, bevacizumab, additional bowel resection, or hand-sewn anastomosis." (PMID 37120533, 2023). "ALB is also associated with the prognosis of many cancers, such as oral cancer, head and neck cancer, and ovarian cancer." (PMID 35113866, 2022). "Ovarian cancer is associated with high serum calcium and low serum albumin in clinical and epidemiologic studies." (PMID 32723677, 2020). "Ovarian cancers cause serum albumin to decline by several mechanisms, including bowel obstruction, loss of albumin to ascites, poor nutrition, and inhibition of albumin synthesis." (PMID 32723677, 2020). "Albumin was previously reported to be statistically significant decreased in the late-stage stages of ovarian cancers and the serum albumin level was associated with poor survival rate." (PMID 32971853, 2020). "Previous studies have demonstrated an association between low serum albumin and increased postoperative complications, as well as reductions in survival in ovarian cancer patients." (PMID 20497581, 2010). "Additionally, Albumin, an important nutritional marker, was found to be associated with ovarian cancer progression." (PMID 40927964, 2025). "Whether high calcium and low albumin predispose to ovarian cancer or reflect existing cancer is unclear." (PMID 32723677, 2020). "A pattern of rising serum calcium and falling serum albumin may be suspicious for ovarian cancer and could be used to refer women for further diagnostic testing, e.g., transvaginal ultrasound." (PMID 32723677, 2020). "In addition, these patients also underwent extended lymph node dissection which, like surgery for ovarian cancer, might be associated with increased albumin losses." (PMID 35410365, 2022). "The risk factors for postoperative morbidity were similar in studies on CRS in ovarian cancers, such as performance status, age, albumin level, and complexity or extensive surgery." (PMID 40095895, 2025). "The effect of albumin on ovarian cancer is complex, and additional approaches are needed to explore the mechanisms." (PMID 38408960, 2024). "Previous large-scale retrospective studies demonstrated that serum albumin levels are a significant independent prognostic marker for patients with ovarian cancer undergoing debulking surgery." (PMID 39050577, 2024). "The present study showed that decreasing albumin levels correspond to an increased probability of unsatisfactory outcomes in debulking surgery for ovarian cancer." (PMID 39050577, 2024). "Three studies have previously investigated the prognostic implication of fibrinogen and albumin in ovarian cancer." (PMID 39409916, 2024). "This retrospective analysis of ovarian cancer patients showed that preoperative albumin levels were the sole significant predictor for grade ≥ 3 complications following the surgical procedure known as aborted primary debulking (AD)." (PMID 39459466, 2024). "Nanoparticle albumin‐bound (nab)‐paclitaxel has an off‐label indication for recurrent ovarian cancer." (PMID 36806695, 2023). "Here we aimed to determine the effect of exposure to SeNPs, coated with either serum albumin or the chitosan to enhance biocompatibility and bioavailability, in two pathologically distinct ovarian cancer cell models on redox response and cell viability." (PMID 36842241, 2023). "Here we demonstrate a novel role for selenium in regulating histone methylation in ovarian cancer cell models treated with inorganic selenium nanoparticles coated with serum albumin or chitosan." (PMID 36842241, 2023).
ovarian carcinoma (continued). "Recently, a study highlighted that high expression of ITGA2 promotes ovarian cancer cell proliferation and resistance to albumin paclitaxel through the AKT/FOXO1 signaling axis." (PMID 37386391, 2023). "Resveratrol–bovine serum albumin NPs were responsible for the induction of cell death pathway in human ovarian cancer cells as well." (PMID 36557789, 2022). "Further, the low concentration of serum ALB is related to the poor survival time of patients with various cancers, as well as for ovarian cancer." (PMID 34997982, 2022). "In this way, several studies in advanced ovarian cancer patients correlated a low serum preoperative albumin and prognostic nutritional index with a worse overall survival." (PMID 35197061, 2022). "Morbidity following surgery for advanced ovarian cancer depends on the complexity of surgery, the experience of the surgeon/unit, and individual patient factors (including age, co-morbidities, and albumin level)." (PMID 36096791, 2022). "In the current study, these CRP and albumin were also extracted as a candidate for prognosis poor outcomes in ovarian cancer patients, comparable to these reports." (PMID 36587139, 2022). "As for the intraperitoneal injection of resveratrol, bovine serum albumin nanoparticles in ovarian cancer nude mice models showed higher concentrations of resveratrol in the blood and increased distribution in tissues such as liver, heart, kidney, and ovary." (PMID 34829589, 2021). "Bacteriochlorin-based photosensitizers conjugated to galactosyl human serum albumin, which binds lectin receptors on ovarian cancer cells, allowed the detection of peritoneal ovarian cancer metastases with very low false positives." (PMID 32899137, 2020). "Encouragingly, our results showed that the sensitivity of ovarian cancer cells to albumin paclitaxel improved significantly after we knocked down ITGA2 expression." (PMID 32202508, 2020). "Collectively, our study suggests that aberrant expression of ITGA2 increases ovarian cancer cell proliferation and enhances ovarian cancer cell resistance to albumin paclitaxel through the AKT/FOXO1 signaling axis." (PMID 32202508, 2020). "Preoperative albumin levels have prognostic significance in renal cancer, head and neck cancer, and ovarian cancer." (PMID 32184816, 2020). "We also found that ITGA2 regulated the phosphorylation of forkhead box O1 (FoxO1) by mediating AKT phosphorylation, which provided a reasonable explanation for ITGA2’s role in ovarian cancer’s resistance to albumin paclitaxel." (PMID 32202508, 2020). "In conclusion, our study of serum calcium and albumin in women pre- and post-diagnosis of ovarian cancer demonstrates that serum calcium levels increased significantly and serum albumin levels decreased significantly." (PMID 32723677, 2020). "As first-line chemotherapy for ovarian cancer, tumor cells have been found to develop resistance to albumin paclitaxel, but the specific mechanism of how this unfolded remained unclear." (PMID 32202508, 2020). "Future longitudinal studies, including those in which changes in calcium and albumin are added to panels of other biomarkers for ovarian cancer, are warranted." (PMID 32723677, 2020). "Pretreatment plasma D-dimer and albumin levels were each identified as prognostic factors for several malignancies, including ovarian cancer; however, few studies have combined them to assess their role in chemoresistance." (PMID 32771026, 2020). "Further validation of the obtained results indicated that five proteins (Serotransferrin, Amyloid A1, Hemopexin, C-reactive protein, Albumin) were differentially expressed in ovarian cancer group." (PMID 30065196, 2018). "The prognostic value of pretreatment albumin has been reported in various human malignancies, including renal cell carcinoma, head and neck cancers, non-small cell lung cancer, ovarian cancer, and adenocarcinoma of the gastric cardia." (PMID 30027102, 2018).
ovarian carcinoma (continued). "Several previous studies reported that pre-operative low serum albumin levels are an independent predictor of poor survival in ovarian cancer." (PMID 28431566, 2017). "This study sought to investigate the association between the preoperative c-reactive protein/albumin ratio (CRP/Alb) and oncological outcomes in ovarian cancer patients." (PMID 28431566, 2017). "Although the usage of albumin is still controversial, previous studies testified that the a low level of serum albumin was an independent prognostic factor adversely affecting survival for non-ovarian cancer patients with MA." (PMID 27103467, 2016). "Albumin-bound paclitaxel has been previously studied in platinum-sensitive recurrent ovarian cancer patients both as a single agent and in combination with carboplatin." (PMID 24804130, 2014). "Comparative proteomics has recently identified afamin, the newest member of the albumin gene family, as a potential biomarker for ovarian cancer." (PMID 23981841, 2013). "In case of the 19 kDa albumin fragment, interaction appeared to be detected only in the pooled urine of patients with ovarian carcinoma compared to that of the controls, while the inverse was observed for CD59, kininogen-1 and the 39 kDa fragment of ITIH4." (PMID 21083881, 2010). "The proteomic profiling of urine samples demonstrated reduced levels of CD59, kininogen-1 and a 39 kDa ITIH4 fragment, as well as the enhanced excretion of a 19 kDa fragment of albumin in patients with ovarian carcinoma compared to control women." (PMID 21083881, 2010). "Proteins found differentially expressed in the serum of ovarian cancer patients after the depletion of high abundance proteins (including albumin and immunoglobulins) were analysed and compared to normal serum using proteomic approaches." (PMID 15199385, 2004). "We have implemented this approach of albumin clearance for the identification of differentially expressed low abundance proteins in the serum of ovarian cancer patients." (PMID 15199385, 2004). "Moreover, research has highlighted the remarkable association of albumin levels, serum ALP, and ECOG score with the outcomes of debulking surgery for epithelial ovarian cancer." (PMID 39050577, 2024). "Moreover, resveratrol–bovine serum albumin nanoparticles trigger human ovarian cancer cell line apoptosis by activating caspase." (PMID 34829589, 2021). "Albumin is a significant prognostic factor for overall survival of ovarian cancer." (PMID 32771026, 2020). "This supports the view that changes in serum calcium and albumin may be useful in the early detection of ovarian cancer." (PMID 32723677, 2020). "We observed a large decline in serum albumin post-diagnosis of ovarian cancer (~ 20%)." (PMID 32723677, 2020). "If confirmed, they suggest that longitudinal changes in serum calcium and albumin could play a role in ovarian cancer screening/early detection." (PMID 32723677, 2020). "Test the hypothesis that serum calcium increases and serum albumin decreases in women who develop ovarian cancer." (PMID 32723677, 2020). "Data from population-based studies suggest that serum calcium and albumin could serve as ovarian cancer biomarkers." (PMID 32723677, 2020). "The finding that levels of serum calcium and albumin discriminate malignant from benign ovarian masses in the surgical setting suggests that these analytes might identify ovarian cancers in a screening setting." (PMID 32723677, 2020). "Furthermore, Zhang and colleagues presumed that preoperative PLR was superior to the other SIR markers (CA-125, NLR, fibrinogen, CRP, and albumin) as a predictor of survival in ovarian cancer patients." (PMID 27821183, 2016). "Nevertheless, in spite of many factors potentially influencing the results, there still may be a relation with MDS itself, since alterations in both ITIH4 and albumin fragments were observed to be related to ovarian carcinoma." (PMID 24958999, 2014).
ovarian carcinoma (continued). "The different altered levels of CD59, kininogen-1 and fragments of ITIH4 and albumin in the urine of patients with ovarian carcinoma, relative to the controls, was confirmed when their 2-DE urine protein profiles were subjected to image analysis using the Image Master 2 D Platinum Software 7.0." (PMID 21083881, 2010). "A study investigating the prognostic role of serum albumin in patients with ovarian cancer treated in an integrative cancer treatment setting found that every one gm/dL increase in serum albumin was associated with a RR of 0.39 (95% CI: 0.29 to 0.53; p < 0.001)." (PMID 21176210, 2010). "Significant reduced levels of CD59, kininogen-1 and a 39 kDa fragment of inter-alpha-trypsin inhibitor heavy chain H4 (ITIH4), and enhanced excretion of a 19 kDa fragment of albumin, were detected in the urine of patients with ovarian carcinoma compared to the control subjects." (PMID 21083881, 2010). "CD59, kininogen-1 and fragments of ITIH4 and albumin may be used as complementary biomarkers in the development of new noninvasive protocols for diagnosis and screening of ovarian carcinoma." (PMID 21083881, 2010). "In the present proteomic profiling study, the significant reduced excretion of CD59, kininogen-1 and a 39 kDa fragment of ITIH4, and the enhanced levels of a 19 kDa fragment of albumin were detected in the urine samples of patients with ovarian carcinoma relative to those of the control subjects." (PMID 21083881, 2010). "Therefore, it is easy to understand the fact that the CRP/albumin ratio is considered a significant prognostic factor for advanced-stage ovarian cancer patients, with a higher value of this parameter being considered as a sign of the biological decline in ovarian cancer patients." (PMID 39061143, 2024). "This study aimed to compare the efficacy of albumin-bound paclitaxel combined with carboplatin (Nab-TC) with that of traditional solvent-based paclitaxel combined with carboplatin (TC) as neoadjuvant chemotherapy (NAC) regimens for primary epithelial ovarian cancer." (PMID 35690772, 2022). "There are some measurable biomarkers of increased risk of VTE in ovarian cancer, such as elevated platelet count, white blood cell counts, d-dimer and CA125 level, decreased hemoglobin and albumin levels preoperatively, and elevated d-dimer and decreased albumin postoperatively." (PMID 33766002, 2021). "In early stage ovarian cancer, the fall in serum albumin likely results from metabolic factors secreted by ovarian cells, including interleukin-6 (IL-6), an inflammatory cytokine that inhibits the synthesis of albumin by hepatocytes and promotes the metastasis of ovarian cancer cells." (PMID 32723677, 2020). "Longitudinal changes in calcium and albumin may be useful in ovarian cancer early detection." (PMID 32723677, 2020). "Since the 19 kDa albumin fragment was present only in trace quantities in the urine of the control subjects, it may be used as a complementary urine biomarker to differentiate ovarian carcinoma patients from healthy individuals." (PMID 21083881, 2010). "In our study, we determined the changes in the oxidative stress (OxS) biomarkers, thiol-disulfide (TD) homeostasis and ischemia-modified albumin (IMA) levels, in patients diagnosed with ovarian carcinoma before and after chemotherapy." (PMID 40473830, 2025). "Albumin-bound paclitaxel (ABP) was tested in combination with bevacizumab, a monoclonal antibody, for the treatment of platinum-resistant recurrent ovarian cancer." (PMID 39941780, 2025). "This study aims to investigate the correlation betweenmalnutrition, assessed through L3 SMI and serum albumin levels and the occurrence of CIPN in ovarian cancer patients receivingpaclitaxel and carboplatin." (PMID 41393484, 2025). "The relationship between nutritional parameters (L3 SMI and albumin) and the incidence of chemotherapy-induced peripheral neuropathy(CIPN) in ovarian cancer patients treated with paclitaxel and carboplatin." (PMID 41393484, 2025).
ovarian carcinoma (continued). "A seven-hub-molecule-signature model (HIBCH, HIST1H2BK, ALB, EIF3E, RPS20, RRAS2, and RPL23A) from a multivariate regression analysis can predict the survival risks of ovarian cancer." (PMID 35498135, 2022). "A seven-hub-molecule-signature model (RRAS2, HIST1H2BK, ALB, RPL23A, HIBCH, RPS20, and EIF3E) from those 1198 mtDEPs is established to predict the survival time of ovarian cancer." (PMID 35498135, 2022). "Compared to the polymer–platinum conjugate without albumin coating, the albumin-coated polymer–platinum conjugate can significantly increase the uptake rate of ovarian cancer cells and enhance their cell toxicity." (PMID 36678653, 2022). "Thus, for prognostic prediction of ovarian cancer, preoperative PLR is better than CA125, NLR, fibrinogen, CRP, and albumin levels." (PMID 35464000, 2022). "We emphasize that this is a pilot study and that it does not validate the use of serum calcium and albumin as part of a screening strategy for ovarian cancer." (PMID 32723677, 2020). "Although low albumin-lymphocyte score (ALS) and skeletal muscle index (SMI) are known to be associated with negative outcomes in patients with ovarian cancer (OC) undergoing primary debulking surgery, the usefulness for predicting prognosis remains unclear." (PMID 42064053, 2026). "The search terms were set to “ovarian neoplasms” OR “ovarian cancer” OR “cancer of ovary” AND “neutrophil-to-lymphocyte ratio,” “platelet-to-lymphocyte ratio,” “monocyte-to-lymphocyte ratio,” “systemic inflammation Index,” “C-reactive protein albumin ratio,” “prognostic nutritional index”." (PMID 36759864, 2023). "In addition, lower serum albumin, use of TPN and numbers of complications were all closely related to the length of hospital stay, suggesting that TPN should be considered as a positive treatment method for advanced stage ovarian cancer patients." (PMID 34246241, 2021). "Advanced ovarian cancer patients are already frail due to their heavy tumor load, age, potential comorbidity (ASA predictive score), and nutritional status (low-preoperative albumin levels), and all of these parameters must be taken into account in the surgical decision." (PMID 22312486, 2010). "However, there are some advantages of using non-antibody targeting agents such as galactosyl serum albumin (GSA), because GSA as a target is ubiquitous among ovarian cancers, whereas it is difficult to find a single antibody that will bind to all types of ovarian cancers." (PMID 34064074, 2021).